DEPDC4 (DEP domain containing 4)
Synonyms: DEP.4; FLJ33505
Tractability: No criterion of Open Targets' tractability assessment is met for any kind of drug.
Gene: Protein-coding gene on chromosome 12 (100,203,669 to 100,267,089, reverse strand). Ensembl gene ENSG00000166153.
Subcellular location (Human Protein Atlas): Microtubules
Gene Ontology:
Biological process: intracellular signal transduction
Genetic constraint (gnomAD): Loss-of-function variants: 38 observed, 35.19 expected, observed/expected ratio (o/e) 1.08, 90% interval 0.83 to 1.41. The upper end of that interval is the gene's LOEUF score, 1.41, which puts it in group 5 of 6, group 1 being the genes least tolerant of losing a copy. Missense variants: 435 observed, 435.66 expected, observed/expected ratio (o/e) 1, 90% interval 0.92 to 1.08. Synonymous variants: 160 observed, 153.02 expected, observed/expected ratio (o/e) 1.05, 90% interval 0.92 to 1.19.
Homologues: Orthologues: chimpanzee DEPDC4 (57% identical), tropical clawed frog depdc4 (46% identical), zebrafish DEPDC4 (45% identical), Caenorhabditis elegans let-99 (16% identical). Paralogues in human: DEPDC7 (35% identical), DEPDC1 (20% identical), DEPDC1B (19% identical).
Diseases named in the same sentence as DEPDC4 in open-access papers:
DEPDC4 is named in the same sentence as 2 diseases in open-access papers, as found by Europe PMC text mining. Sharing a sentence is not in itself a finding about the gene and the disease. The quoted sentences say what the papers report.
atherosclerosis (1 paper, 2020). A disease characterized by the build-up of fatty material and calcium deposition in the arterial wall resulting in partial or complete occlusion of the arterial lumen. "Consistent with VINAS regulation in atherosclerotic mice, DEPDC4 levels declined in coronary arteries of pigs with progression of atherosclerosis and in human carotid plaques with unstable characteristics." (PMID 33021969, 2020). "In summary, these results demonstrate dynamic regulation of the lncRNA VINAS with atherosclerosis progression, that VINAS influences arterial inflammation, and that loss of function of VINAS’s evolutionary conserved lncRNA ortholog DEPDC4 exerts similar antiinflammatory effects." (PMID 33021969, 2020).
DEPDC4 also shares sentences with these, for which no sentence is quoted: tumor (1 paper).